MADCAM1 (mucosal vascular addressin cell adhesion molecule 1)
Diseases named in the same sentence as MADCAM1 in open-access papers (continued):
Sharing a sentence is not in itself a finding about the gene and the disease.
MADCAM1 also shares sentences with these, for which no sentence is quoted: cholangitis (2 papers); colon cancer (2); alcoholic liver diseases (1); anaplastic thyroid carcinoma (1); ankylosing spondylitis (1); Anxiety (1); autoimmune hepatitis (1); cerebrovascular disease (1); gastric mucosa-associated lymphoid tissue lymphoma (1); gastrointestinal tumors (1); Hepatic Injury (1); hepatocellular carcinoma (1); ileitis (1); influenza (1); intestinal diseases (1); invasive breast carcinoma (1); lichen planus (1); liver dysfunctions (1); MALT lymphoma (1); myopathy (1); myositis (1); Obesity (1); pancreatic carcinoma (1); progressive multifocal leukoencephalopathy (1); psychosis (1); Raine syndrome (1); reproductive system disease (1); tonsillitis (1); vasculitis (1).